SLC34A2 (solute carrier family 34 member 2)
Description:
Involved in actively transporting phosphate into cells via Na(+) cotransport.
Synonyms: NaPi-2b; NAPI-3B; NPTIIb; NaPi2b; NAPI-IIb; PULAM
Tractability: Small molecule: a high-quality ligand is known. Antibody: its Gene Ontology location is reachable by antibodies, with high confidence; UniProt places it where antibodies can reach, with medium confidence; UniProt predicts a signal peptide or a membrane-spanning region; the Human Protein Atlas places it where antibodies can reach. PROTAC: a small molecule that binds it is known. Other modalities: a drug acting on it is in phase 2 or 3 trials.
Target class: Transporter; SLC34 family of sodium phosphate co-transporters; Electrochemical transporter; SLC superfamily of solute carriers
Gene: Protein-coding gene on chromosome 4 (25,648,011 to 25,679,132, forward strand). Ensembl gene ENSG00000157765.
Subcellular location: Apical cell membrane
Subcellular location (Human Protein Atlas): Plasma membrane; Cytosol; Nucleoplasm
Pathways (Reactome):
Disease: Defective SLC34A2 causes PALM; Defective SLC34A2 causes pulmonary alveolar microlithiasis (PALM)
Metabolism of proteins: Surfactant metabolism
Transport of small molecules: Type II Na+/Pi cotransporters
Gene Ontology:
Molecular function: phosphate ion binding; sodium ion binding; sodium:phosphate symporter activity
Biological process: intracellular phosphate ion homeostasis; phosphate ion transport; response to estrogen; phosphate ion transmembrane transport; sodium-dependent phosphate transport; sodium ion transmembrane transport
Cellular component: apical plasma membrane; cytosol; membrane; nucleoplasm; plasma membrane; vesicle; brush border; brush border membrane
Genetic constraint (gnomAD): Loss-of-function variants: 39 observed, 49.97 expected, observed/expected ratio (o/e) 0.78, 90% interval 0.6 to 1.02. The upper end of that interval is the gene's LOEUF score, 1.02, which puts it in group 4 of 6, group 1 being the genes least tolerant of losing a copy. Missense variants: 871 observed, 917.82 expected, observed/expected ratio (o/e) 0.95, 90% interval 0.9 to 1. Synonymous variants: 400 observed, 385.12 expected, observed/expected ratio (o/e) 1.04, 90% interval 0.96 to 1.13.
Cancer hallmarks: cell replicative immortality (promotes); invasion and metastasis (promotes); invasion and metastasis (suppresses); proliferative signalling (promotes); suppression of growth (promotes)
Homologues: Orthologues: chimpanzee SLC34A2 (99% identical), macaque SLC34A2 (94% identical), rabbit SLC34A2 (82% identical), rat Slc34a2 (79% identical), dog SLC34A2 (79% identical), mouse Slc34a2 (79% identical), guinea pig SLC34A2 (75% identical), pig SLC34A2 (71% identical), tropical clawed frog slc34a2 (60% identical), Caenorhabditis elegans ZK563.2 (29% identical). Paralogues in human: SLC34A1 (51% identical), SLC34A3 (44% identical).
Diseases named in the same sentence as SLC34A2 in open-access papers:
SLC34A2 is named in the same sentence as 87 diseases in open-access papers, as found by Europe PMC text mining. Sharing a sentence is not in itself a finding about the gene and the disease. The quoted sentences say what the papers report.
ovarian carcinoma (34 papers, 2010 to 2026). A malignant neoplasm originating from the surface ovarian epithelium. "Genomic DNA sequencing was conducted on blood samples from patients with ovarian carcinoma, breast cancer, and renal carcinoma to access the frequency of germline mutations in the SLC34A2 gene region encoding the MX35 epitope." (PMID 40265411, 2025). "Utilizing SLC34A2 as a biomarker in ovarian cancer could help to address the challenges associated with early stage ovarian cancer diagnosis, which could drastically improve patient outcomes." (PMID 40836974, 2024). "SLC34A2 is also regulated by PAX8, a master transcription factor associated with ovarian cancer cell survival and the development of female reproductive systems, suggesting that SLC34A2 may play an important role in tumorigenesis." (PMID 40836974, 2024). "SLC34A2 typically has stable expression throughout ovarian cancer disease pathogenesis and treatment, as evidenced by the consistent SLC34A2 expression observed in longitudinal tissue samples." (PMID 40836974, 2024). "SLC34A2 was proved to have an evident effect in the progression of several types of cancers, such as in ovarian cancer, breast cancer and non-small cell lung cancer." (PMID 32429941, 2020). "The gene and protein expression of SLC34A2/NaPi2b were analyzed in ovarian carcinoma tissues by QPCR (n = 73) and immunohistochemistry (n = 136)." (PMID 28464843, 2017). "SLC34A2 is overexpressed in multiple cancer types, including lung, ovarian, and thyroid cancers and identified as potential therapeutic target for non-small cell lung and Ovarian cancer." (PMID 32164602, 2020). "Besides, recent research reported that SLC34A2 was down-regulated in breast cancer, but overexpression of SLC34A2 was detected in ovarian cancer and papillary thyroid cancer." (PMID 26156586, 2015). "Furthermore, compared to genetic expression in normal tissue, the sodium phosphate cotransporter NaPi2b (encoded by the SLC34A2 gene) is overexpressed in cancer cells of the breast, lung, and thyroid, and NaPi2b overexpression was also found in ovarian carcinomas." (PMID 39330354, 2024). "Preclinical development of an anti-NaPi2b (SLC34A2) antibody-drug conjugate as a therapeutic for non-small cell lung and ovarian cancers has progressed to the clinical stage." (PMID 41211819, 2025). "One of these very attractive targets for cancer therapy is the sodium-dependent phosphate transporter 2B (SLC34A2, NaPi2b, NaPi-IIb, and NPT2) which is overexpressed in several malignancies, including ovarian carcinomas, lung, thyroid, and colorectal cancers." (PMID 35911971, 2022). "MX35 is a murine IgG mAb targeting the NaPi2b (SLC34A2) cell surface glycoprotein, which is expressed in >90% of human epithelial ovarian cancers." (PMID 36687417, 2022). "In our study, the IHC expression of SLC34A2 increased in PTC samples as compared to normal thyroid tissue, which is similar to the expression pattern observed in ovarian cancer, breast cancer, and osteosarcoma." (PMID 34336552, 2021). "Although each alteration is infrequent, ROS1 fusions with many kinds of 5′ partner genes (CCDC6, CD74, EZR, KDELR2, LRIG3, SDC4, SLC34A2 and TPM3) have been reported in lung, brain, biliary tract, and ovarian cancers." (PMID 23418494, 2013). "In addition to PAX8, COPA complemented with pan-cancer analysis prioritized eight other lineage-restricted outliers (CDH6, CLDN16, FGF18, FOLR1, SLC34A2, SOX17, SPON1, WNT7A) displaying largely confined gene expression in ovarian cancer cell lines and tumor specimens." (PMID 31050342, 2019).
lung cancer (31 papers, 2013 to 2025). A malignant neoplasm involving the lung. "For example, SLC34A2 is overexpressed in gastric cancer stem cell-like cells, which are “regarded as the major cause of cancer recurrence”; this is also the case in lung cancer stem cell-like cells from tumors in primary non-small cell lung cancer." (PMID 40643473, 2025). "SLC34A2, a pH-sensitive sodium-dependent phosphate transporter, is associated with lung cancer, and the SLC34A2-ROS1 fusion gene can induce crizotinib resistance and enhance carcinogenicity." (PMID 40433361, 2025). "A previous study has shown that the SLC34A2 level is upregulated in lung tissues 5, and mutations of the SLC34A2 gene are associated with pulmonary alveolar microlithiasis 6 and lung cancer." (PMID 30868061, 2019). "The present study also indicated that the relative mechanisms of SLC34A2 in A549 lung cancer may be associated with the activation of the complement alternative pathway (C3 and C4b) and upregulation of the expression of SELENBP1, TXNIP, PDZK1IP1 and DUSP6." (PMID 25017204, 2014). "SLC34A2 is a phosphate transporter, whose up-regulation has shown inhibitory effects on cell growth, migration, and invasiveness in lung cancer; its apoptotic effect is likely related to phosphate re-uptake into the cell." (PMID 40332279, 2025). "Traditionally, SLC34A2 has been widely recognized as a cancer cell marker in ovarian and lung cancers." (PMID 41211819, 2025). "It has been reported that downregulation of SLC34A2 successfully suppresses lung cancer growth, reduces cancer cell proliferation and angiogenesis, and promotes apoptosis." (PMID 39602465, 2024). "PC (16:0/16:0) was identified as a marker for pneumonia or lung cancer diagnosis due to the immune response with the anti-SLC34A2 antibody, which was a specific marker of type II alveolar epithelial cells." (PMID 35883671, 2022). "It was revealed that in lung cancer, SLC34A2 induces resistance to crizotinib when it undergoes molecular re-arrangement with ROS-1, a tyrosine kinase receptor." (PMID 34944522, 2021). "Among the lung cancer DCB genes, many are associated with surfactant proteins (e.g., SFTA3, SFTPA2, SLC34A2, and BPIFA1), which function to lower surface tension at the air/liquid interface in alveolar cells." (PMID 33883548, 2021). "Nevertheless, SLC34A2 has been reported to be downregulated in some other cancer types, namely, renal cell carcinoma and nonsmall cell lung cancer." (PMID 34336552, 2021). "The present study has provided further insights into the effects and mechanisms of SLC34A2 in lung cancer." (PMID 25017204, 2014). "The AT II cell-like A549 human lung adenocarcinoma cell line was then selected for further identification of the biological functions of SLC34A2 in lung cancer cells." (PMID 25017204, 2014). "Previous studies have demonstrated that the expression of SLC34A2 between normal lung tissue and lung cancer tissue was significantly different." (PMID 25017204, 2014). "The present study further elucidated the effects and mechanisms of SLC34A2 in the generation and development of lung cancer." (PMID 25017204, 2014). "The present study preliminarily revealed the effects and mechanisms of SLC34A2 against A549 lung adenocarcinoma cells in vitro, and provided insights into the effects and mechanisms of SLC34A2 in the generation and development of lung cancer." (PMID 25017204, 2014). "GTx-186 and crizotinib inhibited the proliferation of HCC78 lung cancer cells, which harbors SLC34A2:ROS1 fusion and are dependent on ROS1 for growth, with an IC50 value of 293 nM and 495 nM, respectively." (PMID 24386191, 2013). "However, other than its role as a cancer cell marker, the potential contribution of SLC34A2 overexpression to the development of ovarian and lung cancer remains largely unexplored." (PMID 41211819, 2025).
lung cancer (continued). "Hence, this specific cluster and its distinct gene expression markers (GPRC5A, NAPSA, and SLC34A2) hold promise as prognostic indicators for lung cancer, a prominent source of brain metastases." (PMID 39058687, 2024). "Recent studies suggested that anomalous expression of SLC34A2 might promote tumorigenesis of lung cancer by the activation of PI3K-Akt and Ras/Raf/MEK/ Erk pathways." (PMID 26156586, 2015). "However, at present, the effects and molecular mechanisms of SLC34A2 in the initiation and progression of lung cancer remain to be elucidated." (PMID 25017204, 2014). "In addition, studies have reported that SLC34A2 may inhibit the growth, invasion, and migration of lung cancer cells through PI3K/Akt and Ras/Raf/MEK signaling pathways, by acting as a tumor suppressor." (PMID 37035196, 2023). "Also, recent studies have reported that SLC34A2 plays a key role in lung cancer." (PMID 37035196, 2023). "Moreover, recent studies reported that SLC34A2 played a critical role in lung cancer." (PMID 26910912, 2016). "Therefore, we supposed that SLC34A2, which played a pivotal role in embryonic development and the fetal lung development, might participate in the tumorigenesis and progression of lung cancer." (PMID 26156586, 2015). "Of the remaining 493 LUAD cases, the three studies showed no fusions involving any of the recurrent genes, while SplitFusion detected two cases with SLC34A2::ROS1 fusion, an indication for ROS1-targeted therapy in lung cancer patients." (PMID 40041857, 2025). "Upregulation of MEG3 promotes the protein level of solute carrier family 34 member 2 (SLC34A2) and curbs migration and invasion in lung cancer cells and lung CSCs by sponging miR-650." (PMID 39170516, 2024). "So, MEG3 as a ceRNA plays an important role in the stem cell-like state of lung cancer cells and inhibits migration and invasion in NSCLC via the miR-650/SLC34A2 axis." (PMID 39170516, 2024). "In lung cancers, fusions with CD74 (83/216, 38.4%), EZR (28/216, 13.0%), SDC4 (26/216, 12.0%), and SLC34A2 (26/216, 12.0%) were highly frequent." (PMID 36369474, 2022). "SLC34A2 had been reported to be down-regulated in human NSCLC cells and patient tissues, and played a significant role in lung cancer." (PMID 26910912, 2016). "Similarly, this DCB subtype specificity also extends to lung cancer: 4 of the 6 lung DCB genes (CXCL17, SFTA3, SFTPA2, and SLC34A2) were upregulated in the plasma of patients with lung adenocarcinoma compared to those with squamous cell carcinoma." (PMID 33883548, 2021). "Because in lung, the expression of SLC34A2 was only found in ATII cells and ATII cells might be the origin of several types of lung cancer." (PMID 26156586, 2015). "However, the researches about the function of SLC34A2 in tumorigenesis and development, especially the relationship between SLC34A2 and lung cancer, have not been reported until now." (PMID 26156586, 2015). "Also, our lab previously reported that SLC34A2 was down-regulated in human NSCLC tumor tissues and cells, and might act as tumor suppressor by inhibiting the growth, invasion and migration of lung cancer cells through the PI3K-Akt-mTOR and Ras-Raf-MEK-ERK signaling pathway." (PMID 26910912, 2016).
breast carcinoma (19 papers, 2013 to 2025). "Previous studies have suggested that the tumorigenesis of several types of cancer might be associated with abnormal expression of SLC34A2, including papillary thyroid, ovarian and breast cancer." (PMID 25017204, 2014). "SLC34A2 overexpression is an independent prognostic indicator in bladder cancer 8 and breast cancer." (PMID 30868061, 2019). "It was found that SLC34A2 contributed to the maintaining of stem cell-like phenotypes in breast cancer and non-small-cell lung cancer." (PMID 30038060, 2019). "SLC34A2 was highly expressed in thyroid cancer and breast cancer, but lowly expressed in non-small cell lung carcinomas tissues." (PMID 26910912, 2016). "It was mentioned that SLC34A2 could influence chemotherapy and could establish reasoning for a targeting pathway, and the downregulation of SLC34A2 could play a role in breast cancer progression." (PMID 34944522, 2021). "SLC34A2 was recently identified by sera-screening as being an antigen recognised by sera from patients with immunologically ‘hot’ colorectal cancer and has been shown to play a role in the chemoresistance observed in breast cancer patients." (PMID 32992503, 2020). "ITPR3 encodes an intracellular Ca2+ release channel and is upregulated in actively invading cancer cells and in invasive margin of tumors in colorectal cancer whereas SLC34A2, a sodium/phosphate cotransporter, promotes calcium-phosphate calcifications involved in the development of breast cancer." (PMID 26625260, 2015). "In addition it has been shown that breast cancer cells express high levels of the NaPi-IIb carrier (SLC34A2), suggesting that this carrier may play a role in breast cancer progression." (PMID 29415049, 2018). "CypA/CD147 activation induces CSC features in breast cancer cells through the STAT3 and solute carrier family 34 member 2 (SLC34A2)/phosphatidylinositol-3-kinase (PI3K)/AKT/SRY-box transcription factor 2 (SOX2) signaling pathways." (PMID 36902161, 2023).
pulmonary alveolar microlithiasis (17 papers, 2010 to 2026). Pulmonary alveolar microlithiasis is a disorder in which tiny fragments (microliths) of calcium phosphate gradually accumulate in the small air sacs (alveoli) of the lungs. "Given the confirmed autosomal recessive inheritance of pulmonary alveolar microlithiasis due to an SLC34A2 mutation, the patient and family were counselled about the hereditary nature of the disease." (PMID 41561266, 2025). "SLC34A2 encodes a sodium-dependent phosphate transporter, and its mutations cause pulmonary alveolar microlithiasis, a rare disease characterized by the deposition of calcium phosphate microliths in the lungs." (PMID 41211819, 2025). "Pulmonary alveolar microlithiasis (PAM) is a rare autosomal recessive lung disease caused by variants in the SLC34A2 gene encoding the sodium-dependent phosphate transport protein 2B, NaPi-2b." (PMID 37259144, 2023). "Variants in SLC34A2 encoding the sodium-dependent phosphate transport protein 2b (NaPi-IIb) cause the rare lung disease pulmonary alveolar microlithiasis (PAM)." (PMID 35443721, 2022). "Mutations in SLC34A2 are associated with pulmonary alveolar microlithiasis, and recently, dysregulation of NaPi-IIb has been implicated in tumorigenesis and progression of non-small cell lung cancer." (PMID 30343332, 2019). "Mutations in SLC34A2 (solute carrier family 34, member 2), a sodium phosphate co-transporter specifically expressed in type II alveolar cells, cause pulmonary alveolar microlithiasis." (PMID 22916088, 2012). "Mutations in SLC34A2 may cause pulmonary alveolar microlithiasis." (PMID 23741331, 2013). "Pulmonary alveolar microlithiasis (PAM), a rare disorder caused by SLC34A2 mutations, demonstrates clinical-radiological discordance." (PMID 41878462, 2026). "Some research showed that mutations in SLC34A2 caused Pulmonary Alveolar Microlithiasis (PAM) and anomalous expression of SLC34A2 was responsible for some other diseases such as hypophosphatemia, infertility and Testicular Microlithiasis (TM)." (PMID 26156586, 2015). "Homozygosity mapping has power to identify a disease-causing gene in as few as 3 patients, and we have indeed identified the SLC34A2 gene in pulmonary alveolar microlithiasis and the OPTN gene in the amyotrophic lateral sclerosis both in 3 patients." (PMID 21106127, 2010). "The search terms used were 'pulmonary alveolar microlithiasis' AND 'SLC34A2'." (PMID 37259144, 2023). "The preliminary version of the algorithm described here has been used to prove that the SLC34A2 gene is responsible for pulmonary alveolar microlithiasis; the current version has been used to show that the OPTN gene is responsible for amyotrophic lateral sclerosis." (PMID 21106127, 2010). "Pulmonary alveolar microlithiasis (PAM) is a fascinating, rare lung disease, first described in 1686 and later named as Pulmonary Alveolar Microlithiasis in 1933 by Puhr.It is an autosomal recessive condition; mutations in the SLC34A2 gene have been identified as the culprit in familial cases." (PMID 41561266, 2025). "However, in SLC34A2-intestinal-specific knockout mice, phosphatemia remains normal, and human inactivating mutations in SLC34A2 cause pulmonary alveolar microlithiasis, with an exclusive lung phenotype without hypophosphatemia and without evidence of intestinal phosphate absorption alterations." (PMID 34071837, 2021).
non-small cell lung carcinoma (11 papers, 2011 to 2021). A group of at least three distinct histological types of lung cancer, including non-small cell squamous cell carcinoma, adenocarcinoma, and large cell carcinoma. "Anti-NaPi2b antibody-drug conjugate (ADC), a targeted ADC for SLC34A2, was also proven to be effective and safe in non-small cell lung cancer and ovarian cancer." (PMID 33613767, 2021). "HCC78, a non-small cell lung cancer cell line, which contains SLC34A2-ROS fusion, expresses both FIG and ROS gene." (PMID 21253578, 2011). "SLC34A2 strongly inhibits tumor growth and metastasis ability in non-small-cell lung cancer." (PMID 28678795, 2017). "The gene fusion of SLC34A2 and ROS1 played an important role in the progression of non-small cell lung cancer." (PMID 32429941, 2020).